USP24 (ubiquitin specific peptidase 24)
Diseases named in the same sentence as USP24 in open-access papers (continued):
Sharing a sentence is not in itself a finding about the gene and the disease.
mood disorder (1 paper, 2022). A cognitive disorder a disturbance in which the person's mood is hypothesized to be the main underlying feature. "Although our previous study demonstrated an association between the PCSK9 locus and mood disorder-related traits, here we provide evidence that gene-expression modulation of USP24 –and not PCSK9 –is responsible for the causal effects on mood instability, and neuroticism scores." (PMID 36580462, 2022).
Obesity (1 paper, 2025). Accumulation of substantial excess body fat. "After 19 weeks of ND or HFD feeding, USP24WT HFD-fed mice were larger than USP24C1695A HFD-fed mice were, suggesting that the loss of USP24 enzyme activity inhibited obesity." (PMID 40448065, 2025). "The data indicated that visceral fat surrounded the kidneys in HFD-fed mice but was nearly abolished under USP24-i-101 treatment, suggesting that targeting USP24 dramatically inhibited obesity." (PMID 40448065, 2025). "USP24-i-101 targeting USP24-induced autophagy may also be involved in obesity." (PMID 40448065, 2025). "USP24 upregulation stabilizes PKA-Cα and p300 to activate related pathways involved in lipid metabolism, inflammation, and fibrosis, making it a potential therapeutic target for metabolic disorders such as obesity and Metabolic Associated Fatty Liver Disease (MAFLD)." (PMID 40448065, 2025). "We also studied USP24 and PKA-Cα expression in clinical cohorts with obesity using the TCGA database." (PMID 40448065, 2025).
splenic marginal zone lymphoma (1 paper, 2024). Splenic marginal zone lymphoma is a rare, indolent B-cell non-Hodgkin lymphoma characterized by abnormal clonal proliferation of mature B-lymphocytes with involvement in the spleen, bone marrow and, frequently, the blood. "It was also found that enhanced USP24 expression was regularly observed in the interfollicular zones of splenic marginal zone lymphoma (SMZL) patients." (PMID 39664521, 2024).
type 2 diabetes (1 paper, 2025). "Finally, other disease models, such as type 2 diabetes and neurodegenerative diseases, will be used to study the effect of targeting USP24 with USP24-i-101 on the inhibition these diseases." (PMID 40448065, 2025).
tumor (26 papers, 2016 to 2025). "We observed that the tumor-killing effects of Usp24-deficient OT-1 T cells were comparable to anti-PD-1 antibody (α-PD-1) treatment alone." (PMID 40238877, 2025). "The loss of USP24 significantly enhanced the cytotoxic effect of Taxol to reduce tumor size and tumor weight." (PMID 33846536, 2021). "Recently, we also found that USP24 is upregulated in tumor-associated macrophages to promote cancer malignancy." (PMID 33846536, 2021). "Further studies should help identify the role of USP24-mediated post-translational modification in the interaction of tumor cells and tumor associated microenvironment." (PMID 32354135, 2020). "The IL-6 levels secreted from M2 macrophages and A549 cells decreased after USP24 knockdown, suggesting that USP24 upregulation in the tumor-associated microenvironment and cancer cells during tumorigenesis increased IL-6 expression." (PMID 30266897, 2018). "The variants 930C/T and 7656T/C were increased in tumor samples and were found to induce USP24 expression by stabilizing RNA." (PMID 27516771, 2016). "Furthermore, USPs can control cytokine release patterns, with USP24 increasing IL-6 expression in tumor-associated macrophages (TAMs), whereas USP4, USP7, USP13, and USP19 can stabilize the release of anti-inflammatory receptors or cytokines." (PMID 38613804, 2024). "Furthermore, the overexpression of GFP-USP24 caused anaphase bridge and ultrafine bridge formation, which implies that USP24 induces genomic instability and thereby increases the tumor mutation burden (TMB)." (PMID 33846536, 2021). "Because IL-6 can activate the NF-κB pathway to express several inflammatory-related genes, including cytokines, USP24-mediated IL-6 expression might be crucial to control the other cytokines in the tumor-associated microenvironment." (PMID 30266897, 2018). "USP24 strongly co-localized with CD68, implying that USP24 might be highly expressed in tumor-associated M2 macrophages and might be involved in tumor-associated macrophage-mediated cancer progression." (PMID 30266897, 2018). "Furthermore, although the tumor-associated microenvironment is extremely important to the metastatic process, the function of USP24 in the tumor-associated microenvironment remains unclear." (PMID 30266897, 2018). "However, whether USP24 levels are also affected in other cell types such as fibroblasts and adipocytes within the tumor-associated microenvironment remains unknown and requires future clarification." (PMID 30266897, 2018). "We observed USP24 expression almost overlapping with PD-1 abundance in tumor-infiltrating CD8+ T cells." (PMID 40238877, 2025). "S6, O and P), supporting the notion that USP24-i-101 inhibits tumor growth mainly by boosting antitumor immunity." (PMID 40238877, 2025). "Our previous studies found that USP24 shapes the tumor microenvironment (TME) by promoting the secretion of interleukin-6 (IL-6) in tumor-associated macrophages (TAMs) and cancer cells." (PMID 40238877, 2025). "Immunofluorescence (IF) staining demonstrated highly expressed Usp24 in tumor-infiltrating CD8+ T cells with PD-1+Tim-3+ exhaustion features from Usp24WT mice, while it was less frequent in lung tumors from Usp24C1695A mice." (PMID 40238877, 2025). "Given the widespread expression of USP24, future research should comprehensively investigate the differences in USP24 substrates and ferroptosis sensitivity across various tumor types." (PMID 40715045, 2025). "Because tumor heterogeneity is related to drug resistance, herein we studied the role of USP24 in genomic integrity by whole genome sequencing (WGS)." (PMID 38491202, 2024). "Given its role in regulating tumor microenvironment signaling, USP24 has been identified as a potential therapeutic target." (PMID 39664521, 2024). "For instance, although USP24 inhibits the proliferation of tumor cells, it promotes the spread of metastases in other types of malignancies." (PMID 38613804, 2024).
tumor (continued). "Patients receiving intensive chemotherapy of their NBT showed significantly reduced tumor tissue expression of USP24, USP34, MINDY2, USP8, JOSD1, USP52, and USP12 when compared to the observation group." (PMID 37892185, 2023). "USP24 has recently been identified as a novel tumor suppressor in NBT that targets collapsin response mediator protein 2 (CRMP2), which promotes axon growth, guidance, and neuronal polarity but also affects T cell polarization and migration." (PMID 37892185, 2023). "Studies have also demonstrated that USP24 promotes cancer malignancy by inducing IL-6 transcription into tumor-infiltrating leukocytes, vascular endothelial cells, and cancer-associated fibroblasts." (PMID 32354135, 2020). "USP24 has also been shown to be a regulator of tumor microenvironment signaling and has been proposed as a potential therapeutic target due to this role." (PMID 32457837, 2020). "Consistent with in vitro assay, WP1130 treatment also lead to the decreased of USP24 and Mcl-1 levels in Jurkat tumor xenografts." (PMID 30911287, 2019). "In conclusion, USP24 in TAMs is crucial for tumor malignancy, including metastasis and angiogenesis." (PMID 30266897, 2018). "Similarly, pharmacological inhibition of USP24 with WP1130 significantly promoted RSL3-mediated tumor suppression and lipid peroxidation in TNBC cells." (PMID 40715045, 2025). "Additionally, USP24 knockdown enhanced the anti-tumor effects of other GPX4 inhibitors, including ML162, ML210, and FIN56, in MDA-MB-231 cells, while exerting minimal impact on erastin-induced ferroptosis." (PMID 40715045, 2025). "Moreover, cell migration and colony formation assays revealed that USP24 knockdown potentiated the anti-tumor effects of RSL3, reducing both migratory capacity and colony formation in TNBC cells." (PMID 40715045, 2025). "Silencing USP24 enhances ferroptosis-mediated tumor suppression in TNBC cells." (PMID 40715045, 2025). "Researchers at Zhengzhou University believe that USP24 is a tumor suppressor." (PMID 40607251, 2025). "USP24 silencing inhibits tumor growth and metabolic plasticity." (PMID 40977684, 2025). "Recent studies have indicated that inhibiting proline biosynthesis and lipogenesis synergistically suppressed tumor growth, implying that USP24-i-101 targeting USP24 may be effective in inhibiting cancer progression." (PMID 40448065, 2025). "Moreover, studies have shown that USP24 promoted cancer malignant progression by stabilizing p300 and β-TrCP-induced IL-6 in the tumor microenvironment." (PMID 35223996, 2022). "Accordingly, USP24 could function as a tumor suppressor or oncogene in different kind of cancers or at different stage of cancer progression." (PMID 30911287, 2019). "Therefore, during the initiation of tumor formation, EGFR mutations decrease USP24 to increase the degradation of p300 and Bax, and thus repress cell apoptosis." (PMID 27991932, 2017). "Posteriori, the same authors identified an upregulation of USP24 in a number of tumor cell lines." (PMID 27516771, 2016). "Furthermore, given the involvement of additional signaling pathways within tumors, it remains unclear whether USP24 intervention will yield differential responses in normal versus tumor tissues." (PMID 40715045, 2025). "On the basis of multiplex IF-IHC score analysis, USP24 positively correlated with PD-1 in tumor-infiltrating CD8+ T cells, providing clinical validation of USP24-mediated PD-1 expression." (PMID 40238877, 2025). "USP24 knockdown enhanced RSL3-induced tumor suppression, as evidenced by reductions in tumor volume, tumor size, and tumor weight, without affecting the body weight of the mice." (PMID 40715045, 2025). "USP24, a member of the DUB family, is known to contribute to tumor progression by deubiquitinating and stabilizing substrate proteins." (PMID 40715045, 2025).
tumor (continued). "Cox regression analyses revealed a correlation of high intratumoral USP24+PD-1+CD8+ T cells, advanced tumor stage, larger primary tumor size, lymph node, or distant organ metastasis with poor survival outcomes." (PMID 40238877, 2025). "Our findings dissect the mechanism for regulating enhanced PD-1 stability in tumor-infiltrating CD8+ T cells and reveal USP24 as a potential target of antitumor immunotherapy." (PMID 40238877, 2025). "The USP24-specific inhibitor, USP24-i-101 alone or in combination with immunotherapy anti-CTLA4, profoundly reactivates T cell functions in the TME and markedly induces tumor inhibition." (PMID 40238877, 2025). "Considering the possible tumor suppressor role of USP9X and oncogene role of USP24 in T-ALL and the feedback regulation between USP9X and USP24, developing a USP24 specific inhibitor is needed." (PMID 30911287, 2019). "In addition, we found seven other genes recurrently affected by HBV integration in tumour tissue samples: ECE1, EVI5L, KIF13B, MTX1P1, PLXND1, TECR and USP24." (PMID 37400627, 2023). "The data indicated that the tumor area in the gefitinib-induced EGFRL858R*USP24C1695A drug-resistant mice was inhibited compared with that in the gefitinib-induced EGFRL858R*USP24WT drug-resistant mice, indicating that USP24 promotes drug resistance acquired during cancer therapy." (PMID 38491202, 2024). "Besides, dysregulation in post-transcriptional modifications, like ubiquitination enzymes (HUWE1, CUL4A, TRIM25, etc.)and deubiquitination enzymes (USP7, USP10, USP24, etc.)in these PTC tumor samples may also lead to the low consistency." (PMID 38609408, 2024).
cancer (21 papers, 2011 to 2025). A tumor composed of atypical neoplastic, often pleomorphic cells that invade other tissues. "The loss of USP24 in cancer cells and macrophages significantly inhibited the malignant ability of cancer cells, which indicates that USP24 is a potential target for the development of drugs." (PMID 33846536, 2021). "For example, the EGFR mutation and CDK1-mediated kinase activities contribute to USP24 downregulation, resulting in cancer formation by affecting its substrates." (PMID 27991932, 2017). "Thus, loss of USP24 enzyme activity inhibits gefitinib-induced drug resistance by regulating the expression of genes involved in cancer, ECM and other cells around cancer cells." (PMID 38491202, 2024). "We wondered whether NCI677397 induces autophagic cancer cell death and wanted to understand the detailed mechanisms underlying the effects of the USP24 inhibitor; therefore, we performed an RNA‐seq analysis to generate a global mRNA expression profile of NCI677397‐treated in Pt’3R cells." (PMID 38140768, 2024). "Accumulated evidence underscores the pathological role of USP24 in regulating cancer cell stemness, sustained proliferation, metastasis, inhibition of ferroptosis, and drug resistance." (PMID 40238877, 2025). "Collectively, USP24 activity predominantly establishes an immunosuppressive TME to accelerate cancer progression." (PMID 40238877, 2025). "USP24-i-101 inhibits PD-1 in T cells and PD-L1 in cancer cells and subsequently inflames antitumor immunity within the TME." (PMID 40238877, 2025). "Our recent results indicated that USP24 knockout or USP24-i treatment induced autophagy in vivo and in vitro to inhibit the drug resistance of cancers acquired from Taxol or gefitinib treatment." (PMID 38491202, 2024). "In this study, we discovered that a novel ferroptosis inducer (FIN), NCI677397, which is a USP24‐specific inhibitor, is potentially as a new treatment for drug resistance in cancers." (PMID 38140768, 2024). "Our previous studies indicate that USP24 promotes drug resistance acquired through cancer therapy by stabilizing ABC transporters and inducing the genomic instability." (PMID 38491202, 2024). "In summary, targeting USP24 not only regulates cancer cells themselves but also other cells around cancer cells to inhibit drug resistance acquired by cancer therapy." (PMID 38491202, 2024). "A recent study found that high expression of miR-21-5p and USP24 is associated with cancer progression and drug resistance in HCC by promoting autophagy via USP24-mediated SIRT7 ubiquitination." (PMID 39273339, 2024). "A highly positive correlation between USP24 and cancer stemness markers was also found in cancer cell-injected SCID mice." (PMID 33846536, 2021). "Herein, USP24 was knocked down in both cancer cells and macrophages to study the effect of USP24 on cancer malignancy." (PMID 33846536, 2021). "Our previous studies indicated that an increase in USP24 at the late stages of cancer progression promotes cancer malignancy." (PMID 33846536, 2021). "Our findings suggested that screening of a novel-specific USP24 inhibitor to prevent drug resistance during cancer therapy." (PMID 33846536, 2021). "Taken together, it would be better to use the cocktail treatment, USP24 inhibitor, and chemotherapeutic drugs, in the cancer patients before the drug resistance has emerged." (PMID 33846536, 2021). "Because drug resistance is a major factor to trigger the recurrence and malignancy of cancer, the role of USP24 in drug resistance during therapy needs to be clarified." (PMID 33846536, 2021). "Our results in this study indicated that USP24 can promote drug resistance during cancer therapy by stabilizing several ABC transporters and inducing genomic instability." (PMID 33846536, 2021). "The loss of USP24 partially reversed the cytotoxicity of CPT and oxaliplatin in Hone-1R and HCT116R cancer cells, respectively." (PMID 33846536, 2021).
cancer (continued). "Although the function of USP24 is poorly understood, a recent study demonstrated overexpression of USP24 protein in certain cancer types during the later stages of disease progression." (PMID 32354135, 2020). "USP24 can stabilize BRG1, and BRG1 increases the transcriptional activity of USP24, thus modulating cancer progression by both inhibiting proliferation and promoting migratory ability of cancer cells." (PMID 33257797, 2020). "Taken together, these results indeed indicate that USP24-mediated stabilization of BRD-containing proteins is critical for cancer progression." (PMID 33257797, 2020). "Knockdown of USP24 also decreased the protein stability of p300 in M2 macrophages and A549 cancer cells." (PMID 30266897, 2018). "While studying the role of USP24 upregulation in M2 macrophages, we found that USP24 expression in M2 macrophages enhanced cancer metastasis by inducing IL-6 expression." (PMID 30266897, 2018). "In this study, different mechanistic details regarding USP24-mediated IL-6 expression were observed in M2 macrophages and cancer cells." (PMID 30266897, 2018). "In this study, we found that USP24 is not only upregulated in malignant cancer cells but also in M2 macrophages and participates in cancer metastasis by positively regulating IL-6 expression through multiple genetic and epigenetic mechanisms." (PMID 30266897, 2018). "Silencing USP24 increases the cancer formation by inhibiting cellular apoptosis and increasing cellular proliferation." (PMID 27991932, 2017). "In turn, this decrease in USP24 expression reduced the levels of several proteins related to cancer formation and were shown to be substrates of USP24." (PMID 27991932, 2017). "Several proteins have been identified as the substrates of USP24; these proteins regulate cell apoptosis and cell cycle progression, which are important for cancer formation." (PMID 27991932, 2017). "Based on the data in this study and our previous study, we propose that EGFRL858R- and KrasG12D-mediated signaling pathways inhibit USP24 expression, which is beneficial for cancer formation during the early stage." (PMID 27991932, 2017). "Herein, we found that USP24 was downregulated by phosphorylation during the early stage of cancer and the mitotic stage of cell cycle progression to inhibit apoptosis and increase cell cycle progression." (PMID 27991932, 2017). "Based on these findings, we propose that USP24 negatively regulates cancer tumorigenesis but positively controls cancer malignancy." (PMID 27991932, 2017). "Knockdown of USP24 decreases Bax and p300 levels, and reduces Ku70 acetylation, thereby preventing cancer cell apoptosis." (PMID 27991932, 2017). "The function of USP24 in tumors is intricate, with various studies presenting contrasting views on whether USP24 serves as a promoter or suppressor of cancer." (PMID 40607251, 2025). "Previous studies on the role of USP24 in neurodegenerative diseases and cancer progression have been conducted, but its role in MAFLD progression remains unclear." (PMID 40448065, 2025). "Most research on USP24 focuses on cancer progression and neurodegenerative diseases." (PMID 40448065, 2025). "Moreover, we previously demonstrated that USP24 stabilizes p300 to increase IL-6 transcriptional activity in the TAMs and accelerate cancer malignancy." (PMID 40238877, 2025). "Together, USP24 enzyme inactivation promotes T cell activity to restrain cancer progression." (PMID 40238877, 2025). "In this study, we clarified that USP24 inhibitors induced ferroptosis in different cancer types." (PMID 38140768, 2024). "In this study, targeting USP24-induced autophagy was related to PD-L1 degradation in cancer cells." (PMID 38491202, 2024). "Together, USP24 decreased DDR activity during cancer progression to be beneficial for chemotherapy-induced cell death but might induce genomic instability and ultimately leads to drug resistance." (PMID 33846536, 2021).